ESM1 (endothelial cell specific molecule 1)
Diseases named in the same sentence as ESM1 in open-access papers (continued):
Sharing a sentence is not in itself a finding about the gene and the disease.
oral squamous cell carcinoma (5 papers, 2016 to 2023). "In the meantime, The Cancer Genome Atlas bioinformatics database analysis has suggested that ESM-1 expression is apparently increased in oral squamous cell carcinoma patients in contrast with that in normal individuals." (PMID 33482820, 2021). "Since ESM1 has been shown to contribute to tumor progression in multiple tumor types, these data suggested that ESM1 expression may also have a functional role in oral squamous cell carcinoma." (PMID 27683113, 2016). "Here, we investigated the mechanism by which NGFR affects invasion and tumor progression in a murine oral squamous cell carcinoma (MOC) model and identified an important downstream target of NGFR to be a gene called ESM1." (PMID 27683113, 2016). "A recent study revealed that ESM1 could mediate nerve growth factor receptor (NGFR)-induced invasion and metastasis in murine oral squamous cell carcinoma." (PMID 31073279, 2019).
preeclampsia (5 papers, 2020 to 2024). Preeclampsia is a hypertensive disorder of pregnancy that is characterized by new-onset hypertension with proteinuria presenting after 20 weeks of gestation, and depending on mild or severe forms may initially present with severe headache, visual disturbances, and hyperreflexia. "Perhaps most pertinent to the present study, ESM1 has been associated with both maternal and neonatal factors, including gestational diabetes mellitus (GDM), preeclampsia, and birth weight." (PMID 32889533, 2020). "Although a specific angiogenic role for ESM1 in the placenta is not known, it could be involved in spiral artery remodeling and its expression levels have been associated with numerous adverse pregnancy outcomes including preeclampsia and gestational diabetes." (PMID 36695872, 2023).
coronary artery disease (4 papers, 2019 to 2023). "In hypertensive human patients, ESM-1 concentration correlates with the presence and severity of coronary artery disease, and the clinical benefits of ACE inhibitors include lower blood pressure and prevention of cardiovascular disease." (PMID 35790968, 2022). "It has been reported that blood levels of ESM-1 are elevated in patients with coronary artery disease (CAD) or OSA." (PMID 31429753, 2019). "We investigated to assess whether circulating ESM-1 levels are correlated with the presence of coronary artery disease (CAD) in patients with OSA." (PMID 31429753, 2019).
COVID-19 (4 papers, 2022 to 2024). A disease caused by infection with severe acute respiratory syndrome coronavirus 2. "The role of the remaining eight key genes (ALDH1L, EME1, PYGL, NNMT, PHGDH, CD52, CD3D, and ESM1) in COVID-19 and sarcopenia has been less studied, emphasizing their importance in future research." (PMID 38978778, 2024). "ESM-1 has been recognized as a novel biomarker capable of predicting COVID-19 severity, outcome, and related complications." (PMID 37373282, 2023). "ESM-1 levels were measured in the sera of mechanically ventilated critically ill patients, including COVID-19, non-septic, and septic patients." (PMID 37373282, 2023). "Unfortunately, due to the COVID-19 outbreak, the blood samples of the participants in the third trimester were lost, resulting in a lack of data on the serum concentrations of ESM-1 and PLGF." (PMID 36675388, 2023).
gestational diabetes (4 papers, 2020 to 2023). Carbohydrate intolerance first diagnosed during pregnancy. "Previously, we identified a lower DNA methylation degree at genomic sites near the genes ESM1, MS4A3, and TSPAN14 in the blood cells of adolescent offspring exposed to gestational diabetes and/or maternal obesity in utero." (PMID 35740266, 2022).
liver cancer (4 papers, 2022 to 2024). An epithelial or non-epithelial malignant neoplasm that arises from the liver. "To show the function of ESM1 in liver cancer progression, we knocked out ESM1 in H22 and analyzed tumor progression." (PMID 38956432, 2024). "Collectively, in this part we have shown that knockout of Bcl6 increased HCC cancer cell expression of pro-inflammatory genes while decreasing the expression of anti-inflammatory gene expression including ESM1, and ESM1 promotes liver cancer progression." (PMID 38956432, 2024). "We also tested the function of BCL6 overexpression on inflammatory gene expression in mouse liver cancer cell line Hep53.4 and human liver cancer cell line Hep3B with qPCR, which both supported that BCL6 overexpression suppressed inflammatory genes expression which promote ESM1 expression." (PMID 38956432, 2024).
pituitary adenomas (4 papers, 2016 to 2019). "Endothelial cell-specific molecule-1 (ESM-1) is a biomarker associated with tumor progression in pituitary adenoma." (PMID 31455321, 2019). "By contrast, a strong association was found between ESM-1 immunoreactivity in vascular endothelial cells and progression in pituitary adenoma." (PMID 31455321, 2019). "ESM-1 encodes endocan, which is highly expressed in pituitary adenomas and thought to be related to angiogenesis and strongly associated with tumor invasion in pituitary adenoma." (PMID 31796052, 2019). "The association between the tumor invasion of pituitary adenomas and the expression of ESM-1 has been confirmed in several studies; however, the source of functional ESM-1 production and secretion for tumor invasion remains unknown." (PMID 31455321, 2019). "Further, ESM1 has been found to be strongly associated with tumor invasion in pituitary adenomas." (PMID 27683113, 2016). "Our finding of a significant association of vascular ESM-1 expression with invasion might be used as a more objective marker to evaluate the invasiveness of pituitary adenomas; this method would require less resources and instruments and can be widely used in many institutes." (PMID 31455321, 2019). "The relationship among angiogenesis, tumor initiation, and ESM-1 expression in pituitary adenoma should be investigated." (PMID 31455321, 2019). "The relationship among angiogenesis and ESM-1 expression in pituitary adenoma is still unclear." (PMID 31455321, 2019). "In addition to mechanisms underlying the involvement of ESM-1 in angiogenesis, the association between ESM-1 and invasion in pituitary adenoma remains unclear." (PMID 31455321, 2019). "We specifically focused on one type of pituitary adenoma, namely null cell adenoma (NCA) and evaluated the relationship between invasion and ESM-1 expression in both vascular endothelial and adenoma tissues." (PMID 31455321, 2019). "Our purpose is to assess the impact of endocan (endothelial cell specific molecule-1, ESM-1), CD34 and CD105 on pituitary adenoma invasion." (PMID 26809958, 2016).
renal cell carcinoma (4 papers, 2016 to 2026). "To determine the suitability of serum endocan (ESM-1) levels for diagnosing and monitoring renal cell carcinoma (RCC), we measure serum ESM-1 levels in 56 RCC patients who had undergone radical or partial nephrectomies and 56 age- and sex-matched healthy kidney donors." (PMID 29416643, 2018). "Endothelial Cell Specific Molecule 1 (ESM1) could serve as a biomarker for diagnosing and monitoring renal cell carcinoma." (PMID 32899915, 2020).
acute myocardial infarction (3 papers, 2022 to 2025). Necrosis of the myocardium, as a result of interruption of the blood supply to the area. "There are a few reports in the literature concerning the release kinetics of ESM-1 in STEMI patients, with such studies indicating the ESM-1 levels in patients with acute myocardial infarction to be significantly higher than those in the controls, which is consistent with the present results." (PMID 36388167, 2022). "This study explores the effects of anisodamine-tirofiban combined therapy on cardiac function and the expression of serum NGF and ESM-1 in patients with acute myocardial infarction who underwent percutaneous intervention (PCI), to provide a scientific basis for clinical treatment." (PMID 36246689, 2022).
cervical cancer (3 papers, 2022 to 2024). A primary or metastatic malignant neoplasm involving the cervix. "ESM1 was highly expressed in cervical cancer, and the high expression of ESM1 was associated with poor prognosis of cervical cancer patients." (PMID 38954708, 2024). "ESM1 represents as a promising diagnostic marker and potential therapeutic target of cervical cancer." (PMID 36522312, 2022). "ESM1 therefore represents as a promising diagnostic marker and potential therapeutic target of cervical cancer." (PMID 36522312, 2022). "In addition, the association between ESM1 expression and the prognosis of cervical cancer was analyzed based on TCGA database." (PMID 36522312, 2022). "As ZEB1 was a transcription factor, we think this pathway should play a key role, and it will be a strong complement to the knowledge of ESM1 in regulating cervical cancer except angiogenesis pathway and PI3K-Akt/EMT pathway." (PMID 38954708, 2024). "Kaplan-Meier analysis showed that cervical cancer patients with high ESM1 expression had shorter overall survival." (PMID 38954708, 2024). "In this study, high-throughput drug screening was conducted to screen the potential anti-cervical cancer drug based on ESM1, finally, aloe-emodin was identified to be a potential targeted drug of ESM1." (PMID 38954708, 2024). "Exogenous overexpression of ESM1 significantly enhanced the proliferation, invasion and migration of cervical cancer cells." (PMID 38954708, 2024). "In order to explore the specific effects of ESM1 on cervical cancer cells, we first detected the expression level of ESM1 in different human cervical cancer cell lines." (PMID 38954708, 2024). "Immunohistochemical results showed that ESM1 staining intensity was higher in cervical cancer than in healthy tissue." (PMID 38954708, 2024). "Using the median expression value of ESM1 in cervical cancer tissue as cut-off point, 292 patients with cervical cancer were divided into ESM1 high expression group (n = 146) and ESM1 low expression group (n = 146)." (PMID 38954708, 2024). "The analysis of ESM1 expression in cervical cancer and paracancer tissues showed that the average expression level of ESM1 in cervical cancer tissues was higher than that in corresponding paracancer tissues." (PMID 38954708, 2024). "The effects of aloe-emodin on inhibit ESM1 expression and its inhibitory effect on cervical cancer cells in vitro and in vivo were analyzed by the same method." (PMID 38954708, 2024). "The correlation between ESM1 expression and prognosis of cervical cancer patients was analyzed by bioinformatics." (PMID 38954708, 2024). "By interfering the expression of ESM1 with siRNA, we found that ESM1 acts as an oncogene in cervical cancer, promoting the proliferation, invasion and migration of cervical cancer cells." (PMID 38954708, 2024). "Aloe-emodin is a potential treatment for cervical cancer, which can play an anti-tumor role by inhibiting ESM1/ZEB1." (PMID 38954708, 2024). "The clinical significance and potential mechanisms of ESM1 or VEGFα had been individually and collectively investigated and elucidated in an amount of cancer, including cervical cancer, in previous studies." (PMID 37476182, 2023). "As shown, the number of ESM1 mRNA transcripts in the cervical cancer tissues was significantly higher than that in the normal cervical tissues." (PMID 36522312, 2022). "The wound-healing assay as well as “Transwell” and “Matrigel Transwell” assays showed that ESM1 shRNA potently inhibited cervical cancer in vitro cell migration and invasion." (PMID 36522312, 2022). "Conversely, ectopic overexpression of ESM1 did opposite functions and exerted cancer-promoting activity in cervical cancer cells." (PMID 36522312, 2022). "CRISPR/Cas9-mediated ESM1 KO inhibited cervical cancer cell proliferation (EdU-nuclei ratio decreasing) and cell cycle progression (causing G1-S arrest)." (PMID 36522312, 2022).
cervical cancer (continued). "The results of the present study support that overexpressed ESM1 is important for cervical cancer progression, possibly by promoting PI3K-Akt activation and EMT progression." (PMID 36522312, 2022). "ESM1 protein was upregulated in cervical cancer tissues from three representative patients (Patient#1/#3/#6)." (PMID 36522312, 2022). "ESM1 shRNA or KO robustly inhibited cervical cancer cell viability, proliferation, migration, invasion as well as cell cycle progression, while inducing apoptosis." (PMID 36522312, 2022). "Significantly, SYT13 was upregulated in ESM1-overexpressed SiHa and HeLa cervical cancer cells (OE-ESM1)." (PMID 36522312, 2022). "shRNA-mediated silencing of ESM1 downregulated the expression of Vimentin, N-Cadherin and Slug, while upregulating E-Cadherin in cervical cancer cells." (PMID 36522312, 2022). "The representative immunohistochemistry (IHC) assay results further verified ESM1 protein upregulation in cervical cancer tissues of Patient#1." (PMID 36522312, 2022). "After combining all 12 sets of ESM1 blotting data, we found that ESM1 protein expression is significantly upregulated in the cervical cancer tissues (P < 0.0001 vs. “N” tissues)." (PMID 36522312, 2022). "In conclusion, overexpressed ESM1 is important for cervical cancer growth in vitro and in vivo, possibly by promoting PI3K-Akt activation and EMT progression." (PMID 36522312, 2022). "Bioinformatics analysis revealed that ESM1 expression was significantly elevated in human cervical cancer tissues, correlating with patients’ poor prognosis." (PMID 36522312, 2022). "The mice xenograft model was applied to study the potential effect of ESM1 on cervical cancer cell growth in vivo." (PMID 36522312, 2022). "In shESM1-a /shESM1-b-expressing stable cervical cancer cells, ESM1 mRNA expression was decreased significantly." (PMID 36522312, 2022). "Kaplan-Meier survival analysis showed that cervical cancer patients with low ESM1 expression had significantly longer disease-specific survival (DSS) and overall survival." (PMID 36522312, 2022). "ESM1 mRNA was significantly upregulated in 33 cervical cancer tissues compared to 24 normal tissues in GSE9750 dataset." (PMID 36522312, 2022). "Gene Set Enrichment Analysis (GSEA) was employed to analyze the differentially expressed genes (DEGs), by comparing ESM1 high-expression cervical cancer tissues with the ESM1 low-expression cervical cancer tissues retrieved from TCGA database." (PMID 36522312, 2022). "To confirm the bioinformatics results, we tested ESM1 expression in cervical cancer tissues of local patients administrated at our hospital." (PMID 36522312, 2022). "FACS assay results revealed that ESM1 silencing led to significantly increased cervical cancer cells with Annexin V-7AAD positive staining." (PMID 36522312, 2022). "CCK-8 assay results showed that the viability of cervical cancer cells was significantly decreased by silencing of ESM1." (PMID 36522312, 2022). "ESM1 mRNA expression in cervical cancer tumor tissues was about four-fold higher than that in adjacent normal tissues." (PMID 36522312, 2022). "The Cancer Genome Atlas (TCGA) database and the Genotype-Tissue Expression (GTEx) project were consulted to analyze ESM1 transcripts in human cervical cancer tissues." (PMID 36522312, 2022). "Our present study implied ESM1-driven cervical cancer cell progression and EMT by mediating SYT13-dependent activation of PI3K/Akt cascade." (PMID 36522312, 2022). "SYT13 siRNA suppressed migration and invasion of both vector control and ESM1-overexpressed cervical cancer cells." (PMID 36522312, 2022). "First, the number of ESM1 transcripts is significantly higher in TCGA-cervical cancer database, correlating with poor survival, tumor-stage, tumor-grade, and lymphatic vascular invasion." (PMID 36522312, 2022).
cervical cancer (continued). "Future studies will be needed to possibly develop small-molecule inhibitors or antibodies against ESM1, and to test their efficiency against cervical cancer." (PMID 36522312, 2022). "We further explored ESM1 expression in cervical cancer by retrieving the Gene Expression Omnibus (GEO)." (PMID 36522312, 2022). "Further functional studies revealed that ESM1 KO increased Annexin V staining in cervical cancer cells, supporting apoptosis activation." (PMID 36522312, 2022). "Compared to the control cells with the CRISPR/Cas9 empty vector (“Cas9-C”) ESM1 mRNA expression was significantly decreased in the koESM1-cervical cancer cells (“-a/-b/-c” stands for three selections)." (PMID 36522312, 2022). "The potential effect of ESM1 silencing on the primary human cervical cancer cells (“priCC-1”) was studied." (PMID 36522312, 2022). "Subgroup analysis based on different clinical characteristics in TCGA database showed that high expression of ESM1 was positively correlated with the high clinicopathological stage (P < 0.01) and disease classification in cervical cancer patients." (PMID 36522312, 2022). "Whereas ESM1 overexpression by a lentiviral construct accelerated proliferation and migration of cervical cancer cells." (PMID 36522312, 2022). "In this study, we found that aloe-emodin could effectively target the active pocket of ESM1, which meant that aloe-emodin might have potential treatment value in cervical cancer." (PMID 38954708, 2024). "It shows that ESM1 may play a role in promoting cervical cancer by regulating extracellular matrix remodeling, migration and metastasis." (PMID 38954708, 2024). "Results showed that ESM1 was highly expressed in cervical cancer cell lines." (PMID 38954708, 2024). "The silencing of ESM1 expression may inhibit the proliferation, invasion, metastasis and epithelial-mesenchymal transformation of cervical cancer cells by inhibiting ZEB1/PI3K/AKT." (PMID 38954708, 2024). "Overexpression of ESM1 promoted the proliferation and migration of cervical cancer cells." (PMID 38954708, 2024). "The results showed that aloe-emodin could effectively inhibit the proliferation, invasion of cervical cancer, further results demonstrated that aloe-emodin inhibited the ESM1/ZEB1/EMT axis." (PMID 38954708, 2024). "Moreover, ESM1 mRNA and protein expression are upregulated in local cervical cancer tissues and various human cervical cancer cells." (PMID 36522312, 2022). "Indeed, PI3K-Akt cascade and expression of EMT-promoting proteins were decreased after ESM1 silencing in cervical cancer cells, but increased following ESM1 overexpression." (PMID 36522312, 2022). "Together, ESM1 overexpression-induced PI3K-Akt activation as well as cervical cancer cell invasion/ migration might be due to increasing SYT13 expression." (PMID 36522312, 2022). "In vivo, ESM1 knockout hindered SiHa cervical cancer xenograft growth in mice." (PMID 36522312, 2022). "Collectively, these results confirmed that ESM1 is upregulated in cervical cancer cells." (PMID 36522312, 2022). "Furthermore, ESM1 protein was upregulated as well in established cervical cancer cells when compared to that in normal cervical epithelial cells." (PMID 36522312, 2022). "Ectopic ESM1 overexpression in cervical cancer cells increased SYT13 expression." (PMID 36522312, 2022). "Moreover, ESM1 depletion upregulated E-Cadherin, but downregulated N-Cadherin, vimentin, and Slug in human cervical cancer cells and SiHa xenografts tissues." (PMID 36522312, 2022). "Here, the bioinformatics studies and RNA sequencing data revealed that SYT13 could be a primary target of ESM1 in cervical cancer." (PMID 36522312, 2022). "Moreover, ESM1 mRNA and protein upregulation was detected in local cervical cancer tissues and various cervical cancer cells." (PMID 36522312, 2022). "Therefore, ESM1 overexpression is correlated with poor overall survival and major clinicopathological parameters in cervical cancer." (PMID 36522312, 2022).